TENM2 (teneurin transmembrane protein 2)
Description:
Involved in neural development, regulating the establishment of proper connectivity within the nervous system. Acts as a ligand of the ADGRL1 and ADGRL3 receptors that are expressed at the surface of adjacent cells. Promotes the formation of filopodia and enlarged growth cone in neuronal cells. Mediates axon guidance and homophilic and heterophilic cell-cell adhesion. May function as a cellular signal transducer. [Isoform 2]: Acts as a ligand of the ADGRL1 receptor. Mediates axon guidance and heterophilic cell-cell adhesion. [Ten-2 intracellular domain]: Induces gene transcription inhibition.
Synonyms: Ten-2; Ten-m2; KIAA1127; ODZ2; TNM2; TEN2
Tractability: Antibody: UniProt places it where antibodies can reach, with high confidence; its Gene Ontology location is reachable by antibodies, with high confidence; UniProt predicts a signal peptide or a membrane-spanning region. PROTAC: ubiquitination databases record sites on it; its protein half-life has been measured.
Gene: Protein-coding gene on chromosome 5 (166,979,029 to 168,264,157, forward strand). Ensembl gene ENSG00000145934.
Subcellular location: Cell membrane; Presynaptic cell membrane; Postsynaptic cell membrane; Endoplasmic reticulum; Golgi apparatus; Synapse; Cell projection, dendritic spine; Cell projection, filopodium; Cell projection, growth cone; Cell membrane (Isoform 2); Nucleus, PML body (Ten-2 intracellular domain)
Subcellular location (Human Protein Atlas): Nucleoli
Gene Ontology:
Molecular function: protein heterodimerization activity; protein homodimerization activity; signaling receptor binding; calcium ion binding
Biological process: retrograde trans-synaptic signaling by trans-synaptic protein complex; axon guidance; cell-cell adhesion; negative regulation of transcription by RNA polymerase II; positive regulation of filopodium assembly; synaptic membrane adhesion; signal transduction
Cellular component: plasma membrane; cell junction; dendrite; dendritic spine; endoplasmic reticulum; filopodium; glutamatergic synapse; Golgi apparatus; growth cone; neuron projection; nucleus; PML body; postsynaptic membrane; presynaptic membrane; synapse; membrane
Genetic constraint (gnomAD): Loss-of-function variants: 48 observed, 236.68 expected, observed/expected ratio (o/e) 0.2, 90% interval 0.16 to 0.26. The upper end of that interval is the gene's LOEUF score, 0.26, which puts it in group 1 of 6, group 1 being the genes least tolerant of losing a copy. Missense variants: 3,033 observed, 3,764.4 expected, observed/expected ratio (o/e) 0.81, 90% interval 0.78 to 0.83. Synonymous variants: 1,361 observed, 1,480.9 expected, observed/expected ratio (o/e) 0.92, 90% interval 0.88 to 0.96.
Homologues: Orthologues: chimpanzee TENM2 (99% identical), dog TENM2 (99% identical), rabbit TENM2 (99% identical), pig TENM2 (99% identical), guinea pig TENM2 (99% identical), rat Tenm2 (98% identical), mouse Tenm2 (98% identical), macaque TENM2 (94% identical), tropical clawed frog TENM2 (85% identical), zebrafish tenm2a (74% identical), zebrafish tenm2b (72% identical), Drosophila melanogaster Ten-m (34% identical), and 4 more. Paralogues in human: TENM3 (68% identical), TENM4 (63% identical), TENM1 (56% identical), NAGPA (5% identical).
Diseases named in the same sentence as TENM2 in open-access papers:
TENM2 is named in the same sentence as 37 diseases in open-access papers, as found by Europe PMC text mining. Sharing a sentence is not in itself a finding about the gene and the disease. The quoted sentences say what the papers report.
breast carcinoma (4 papers, 2017 to 2023). "Indeed, in a gene expression profiling study performed on normal and cancer-associated fibroblasts derived from breast cancer patients, TENM2 mRNA was one of the large number of genes that were found to be up-regulated." (PMID 33652578, 2021). "Only three variants were observed not only in the affected cousin pair, but also in the other recurrent breast cancer cases sequenced in the same pedigree (in genes TENM2, CCDC136, and MDH2)." (PMID 38136396, 2023). "On the other hand, TENM2 expression analysis across breast cancers provided interesting correlation with poor prognosis of patients that developed metastatic disease." (PMID 29744893, 2018). "Similarly, TENM2 down-regulation has been observed in breast cancer cells that were concomitantly treated with prolactin and 17β-estradiol, stressing the fact that its down-regulation is not related to epigenetic factors." (PMID 33652578, 2021). "We therefore conclude that TENM2 may represent a gene whose transcriptional repression by ZEB1 may reflect an adaptation of breast cancer cells to an intermediate level of malignancy." (PMID 29744893, 2018). "Furthermore, data from a microarray of micro-dissected epithelial cells have displayed significantly reduced TENM2 expression in breast hyperplastic enlarged lobular units, which are histologically considered premalignant precursors of breast cancer, compared to normal terminal duct lobular units." (PMID 33652578, 2021).
cervical cancer (4 papers, 2017 to 2022). A primary or metastatic malignant neoplasm involving the cervix. "By contrast, a tumor suppressor role has been suggested for TENM2 in ovarian, prostate, cervical cancers and stomach tumors." (PMID 33652578, 2021). "Similarly, a comparison of the gene-expression profiles of tumors from early-stage cervical cancer patients, with or without lymph node metastases, has revealed that TENM2 is one of the genes that undergo down-regulated expression." (PMID 33652578, 2021).
MALT lymphoma (4 papers, 2012 to 2018). An indolent, extranodal type of non-Hodgkin lymphoma composed of small B-lymphocytes (centrocyte-like cells). "With regard to translocations substituting 5′-UTR regulatory sequences, placement of a strong IGH promoter upstream of TENM2 was associated with at least 3-fold higher Teneurin-2 transcript levels in MALT lymphomas, as compared to tumors not bearing the translocation." (PMID 30618566, 2018).
ovarian carcinoma (4 papers, 2017 to 2024). A malignant neoplasm originating from the surface ovarian epithelium. "In colorectal, pancreatic, prostate and ovarian cancers, low levels of TENM2 expression are correlated with lower patients’ overall survival." (PMID 33652578, 2021). "While ovarian cancer cells resistant to vincristine have higher TENM2 expression levels compared to parental cells, their cisplatin sensitivity is decreased upon TENM2 down-regulation." (PMID 33652578, 2021). "In the case of ovarian cancer, the analysis of a cohort of serous tumors has revealed that TENM2 expression is significantly lower in poorly differentiated (grade III) and undifferentiated tumors, compared to well differentiated (grade I and II) tumors." (PMID 33652578, 2021). "Notably, low levels of TENM2 expression are correlated with lower patients’ overall survival for colorectal, pancreatic, prostate and ovarian cancers." (PMID 38654044, 2024).
periodontitis (4 papers, 2019 to 2025). An acute or chronic inflammatory process that affects the tissues that surround and support the teeth. "Although gene Tenm2 has been reported to be associated with diseases such as periodontitis and anosmia, the linkage between Tenm2 and diseases was primarily built on the basis of genomic studies." (PMID 36936430, 2023). "TENM2 encoding teneurin-transmembrane protein 2 was strongly associated with periodontitis." (PMID 30547318, 2019). "A total 10,268 SNPs of ten targeted periodontitis genes were analyzed among 2649 SNPs in five genes (TENM2, LDLRAD4, SLC9C2, MFSD1, and A2BP1), and their statistical differences (p < 0.05) are listed." (PMID 30547318, 2019). "The third window, on chr5:166,000,000–167,000,000 (q34), contains the TENM2 gene, which may play a part in the molecular etiology of periodontitis." (PMID 40244243, 2025). "Specifically, if any one of TENM2, A2BP1, LDLRAD4, SLC9C2, or MFSD1 was observed in the patients with periodontitis, obesity and blood pressure have to be treated simultaneously." (PMID 30547318, 2019). "Therefore, if any of TENM2, A2BP1, LDLRAD4, SLC9C2, and MFSD1 is detected in the patients with periodontitis, obesity and blood pressure have to be treated simultaneously." (PMID 30547318, 2019).
neuroblastoma (3 papers, 2017 to 2018). Neuroblastoma (NB) is the most common solid, extracranial childhood tumor. "However, structural aberrations in the TENM3, TENM4 and TENM2 genes were identified in neuroblastoma, and in the case of Ten-4, expression of gene chimeras was demonstrated by RNA-Seq, strongly supporting a functional involvement of these aberrations in tumor development." (PMID 28472127, 2017).
diabetes nephropathy (2 papers, 2022 to 2025). "TENM2, which enables signaling receptor binding activity and cell adhesion molecule binding activity, is involved with renal fibrosis and the development of diabetic kidney disease." (PMID 35630098, 2022). "In recent years, researchers have conducted more and more large‐scale GWAS and Mendelian randomization analysis to explore the genetic variation related to diabetes nephropathy, including UMOD, COL4A3, COL20A1, TENM2, SLC47A1, and so forth." (PMID 40931579, 2025).
nicotine dependence (2 papers, 2020 to 2025). Physical and psychological dependence on nicotine. "Both variants influence nearby gene expression (rs2714700/MAGI2-AS3 in hippocampus; rs1862416/TENM2 in lung), and expression of genes spanning nicotine dependence-associated variants is enriched in cerebellum." (PMID 33144568, 2020). "We observe five genome-wide significant loci, including previously unreported loci MAGI2/GNAI1 (rs2714700) and TENM2 (rs1862416), and extend loci reported for other smoking traits to nicotine dependence." (PMID 33144568, 2020).
Obesity (2 papers, 2019 to 2025). Accumulation of substantial excess body fat. "The intronic variant, rs13155681 (c.226 + 44283C > T) located in TENM2 was associated with the 95th percentile BMI and may mediate obesity through adipocyte differentiation." (PMID 40939575, 2025). "The present study discovered that five genes (A2BP1, TENM2, LDLRAD4, SLC9C2, and MFSD1) were associated with metabolic traits such as obesity and high blood pressures." (PMID 30547318, 2019).
renal fibrosis (2 papers, 2022). A final common manifestation of a wide variety of chronic kidney diseases characterized by glomerulosclerosis and tubulointerstitial fibrosis. "Whereby kidney single-cell RNA sequencing indicated TENM2 expression particularly in podocytes, lower tubular TENM2 expression was associated with renal fibrosis (p=2.0×10−9) and lower eGFR (p=1.6×10−8) in the nephrectomy samples." (PMID 35763030, 2022).
Atrophy (1 paper, 2022). Any weakening or degeneration, especially through lack of use. "Reduced Tenm2, as noted in K18-tau seeded PS/E4H mice, has been associated with atrophy patterns in genetic FTD." (PMID 35440098, 2022).
dementia (1 paper, 2022). Loss of intellectual abilities interfering with an individual's social and occupational functions. "In our study, TENM2 was found to have a tendency of differential expression in the AD vs. no dementia control group in the GSE5281 dataset (logFC = −0.747, adj.p = 0.00366)." (PMID 35892682, 2022).
glioma (1 paper, 2021). A benign or malignant brain and spinal cord tumor that arises from glial cells (astrocytes, oligodendrocytes, ependymal cells). "A conflicting trend can be observed in urothelial, endometrial, head and neck, renal, stomach and thyroid cancers, as well as in glioma and melanoma, in which low levels of TENM2 expression are correlated with better patients’ overall survival." (PMID 33652578, 2021). "TENM2 mRNA down-regulation, compared to normal tissues, has been observed in brain lower grade glioma, in skin cutaneous melanoma, in testicular germ cell tumors, in cervical intraepithelial neoplasia and in esophagus squamous cell carcinoma." (PMID 33652578, 2021).
Hepatic steatosis (1 paper, 2025). Steatosis is a term used to denote lipid accumulation within hepatocytes. "Together, the overexpression of the three genes TENM2, GRIN2C, and ACACB in the CC group would indicate a greater synthesis of fats in the liver, which could lead to the accumulation of these and produce hepatic steatosis." (PMID 40160973, 2025).
lung adenocarcinoma (1 paper, 2021). A carcinoma that arises from the lung and is characterized by the presence of malignant glandular epithelial cells. "The overexpression of TENM2 has also been observed in Erlotinib-resistant lung adenocarcinoma cells, compared to parental cells." (PMID 33652578, 2021). "Cytogenetic rearrangements involving the TENM2 gene have indeed been observed in neuroblastoma, prostate adenocarcinoma, invasive breast carcinoma, lung adenocarcinoma and breast and ovarian serous adenocarcinoma." (PMID 33652578, 2021). "In line with this in silico data, a proteomic analysis of lung-tumor samples has identified TENM2 expression as a marker with which to better classify neoplastic lesions in the lung, as it is highly and homogenously expressed in pleural mesothelioma compared to lung adenocarcinoma cell lines." (PMID 33652578, 2021).
schizophrenia (1 paper, 2025). A major psychotic disorder characterized by abnormalities in the perception or expression of reality. "In contrast, a more limited enrichment was found for “Schizophrenia symptom severity measurement” (p = 0.0003), with only three genes displaying significant associations (RBFOX1, CSMD1, and TENM2)." (PMID 39237719, 2025).
stomach tumors (1 paper, 2021). "Moreover, while the TENM2 protein has been found to be highly expressed in normal squamous cells of the stomach and small intestine, in the majority of stomach tumors, the level of expression of TENM2 protein was either low or undetectable." (PMID 33652578, 2021).
cancer (7 papers, 2015 to 2024). A tumor composed of atypical neoplastic, often pleomorphic cells that invade other tissues. "Interestingly, TENM2 was validated as frequently mutated in this cancer by analyzing data from additional cohorts." (PMID 30618566, 2018). "A possible link between TENM2 deregulation and the drug sensitivity of cancer cells has also been proposed, again with contradictory results." (PMID 33652578, 2021). "As observed for TENM1, the TENM2 gene is frequently altered in tumors, further hinting at its involvement in cancer development and progression." (PMID 33652578, 2021). "In this study, five differentially expressed proteins (DEPs) and eight differentially expressed protein combinations (DEPCs) showed promising performance (area under curve, AUC > 0.900) in pan-cancer identification [e.g., TENM2 (AUC = 0.982), CD36 (AUC = 0.974), and CD36-ITGA1 (AUC = 0.971)]." (PMID 38194998, 2024). "Interestingly, in TNBC cell lines, TENM2 seems to be regulated by the Zinc finger E-box binding homeobox 1 (ZEB1), a transcription regulator with a potential role in cancer progression that is involved in promoting the EMT." (PMID 33652578, 2021). "The identified membrane proteins serve as receptors (EPHB6, ACKR1, and EDNRB) or adhesion molecules (EPCAM) and may enhance antitumor immunity (TENM2 and CLEC‐10A); thus, they may contribute to enhanced mEHT‐induced cancer destruction through regulating the TME related immune response." (PMID 38217262, 2024).
tumor (7 papers, 2017 to 2025). "The possible tumor suppressor role of TENM2 is also suggested by the observation that hepatitis B virus-related insertional mutagenesis, leading to TENM2 gene disruption, is frequently associated with hepatocarcinogenesis." (PMID 33652578, 2021). "Further evidence supporting a possible role for TENM2 deregulation in the tumor microenvironment comes from whole-genome single nucleotide polymorphism profiling, which compared the progressive passages of tumor-derived endothelial cells." (PMID 33652578, 2021). "While all the results described so far focus on the role of TENM2 deregulation in tumor cells, it is worth noting that TENM2 can also be found in the cells of the microenvironment." (PMID 33652578, 2021). "Finally, our data and in silico analyses do not support a methylation-mediated control of Ten-2 and Ten-4 gene expression in tumor cells, despite the presence of potential CpG-rich regions in both TENM2 and TENM4 genomic sequences." (PMID 28472127, 2017). "Nevertheless, poorly differentiated cell lines mimicked upregulated expression of genes (in tumours) such as CAV1, COL4A1, and novel candidates such as TSPAN5, TENM2, C15orf48, PLAU, AHNAK2, FAM129A, PLAU and platelet-specific phosphofructokinase (PFKP)." (PMID 30176945, 2018). "No known function for TENM-1 in TNBC, but if it serves a tumor suppressor role like what has been suggested for TENM2 in various type of tumors then that is consistent with the decreased expression in our FSCN1CON." (PMID 34959629, 2021).
TENM2 also shares sentences with these, for which no sentence is quoted: Alexander disease (1 paper); amyotrophic lateral sclerosis (1); Anosmia (1); bipolar disorder (1); brain disorder (1); chronic kidney disease (1); chronic periodontitis (1); depression (1); fibrosis (1); Impaired glucose tolerance (1); injury (1); intellectual disabilities (1); metastatic disease (1); neurologic disease (1); ovarian tumor (1); serous carcinomas (1); status epilepticus (1); triple-negative breast carcinoma (1).